DNAH9 (dynein axonemal heavy chain 9)
Description:
Force generating protein required for cilia beating in respiratory epithelia. Produces force towards the minus ends of microtubules. Key component of dynein, a family of motor proteins essential for movement along microtubules (By similarity). Dynein has ATPase activity; the force-producing power stroke is thought to occur on release of ADP. Required for structural and functional integrity of cilia.
Synonyms: DNAH17L; DNEL1; KIAA0357; Dnahc9; HL20; HL-20; DNAL1; DYH9; CILD40
Tractability: Small molecule: a structure with a bound ligand is known. Antibody: its Gene Ontology location is reachable by antibodies, with medium confidence. PROTAC: ubiquitination databases record sites on it; its protein half-life has been measured.
Gene: Protein-coding gene on chromosome 17 (11,598,470 to 11,969,748, forward strand). Ensembl gene ENSG00000007174.
Subcellular location: Cytoplasm, cytoskeleton, cilium axoneme; Cell projection, cilium, flagellum
Subcellular location (Human Protein Atlas): End piece; Flagellar centriole; Cytosol
Gene Ontology:
Molecular function: protein binding; dynein intermediate chain binding; dynein light intermediate chain binding; minus-end-directed microtubule motor activity; ATP binding
Biological process: cilium movement; cilium movement involved in cell motility; microtubule-based movement; microtubule-based process
Cellular component: 9+2 motile cilium; axoneme; centriole; distal portion of axoneme; motile cilium; sperm end piece; sperm flagellum; dynein complex; outer dynein arm
Genetic constraint (gnomAD): Loss-of-function variants: 322 observed, 455.46 expected, observed/expected ratio (o/e) 0.71, 90% interval 0.64 to 0.77. The upper end of that interval is the gene's LOEUF score, 0.77, which puts it in group 3 of 6, group 1 being the genes least tolerant of losing a copy. Missense variants: 5,241 observed, 5,599 expected, observed/expected ratio (o/e) 0.94, 90% interval 0.91 to 0.96. Synonymous variants: 2,029 observed, 2,130.4 expected, observed/expected ratio (o/e) 0.95, 90% interval 0.92 to 0.99.
Homologues: Orthologues: chimpanzee DNAH9 (99% identical), macaque DNAH9 (97% identical), dog DNAH9 (88% identical), pig DNAH9 (88% identical), mouse Dnah9 (88% identical), rat Dnah9 (87% identical), guinea pig DNAH9 (87% identical), Drosophila melanogaster Dhc93AB (59% identical), Drosophila melanogaster kl-5 (51% identical), Drosophila melanogaster CG3339 (48% identical), zebrafish dnah9 (6% identical). Paralogues in human: DNAH17 (63% identical), DNAH11 (59% identical), DNAH10 (31% identical), DNAH2 (31% identical), DNAH5 (29% identical), DNAH8 (29% identical), DNAH1 (28% identical), DNAH6 (28% identical), DNAH7 (27% identical), DNAH12 (27% identical), DNAH3 (27% identical), DNAH14 (24% identical), and 3 more.
Diseases named in the same sentence as DNAH9 in open-access papers:
DNAH9 is named in the same sentence as 55 diseases in open-access papers, as found by Europe PMC text mining. Sharing a sentence is not in itself a finding about the gene and the disease. The quoted sentences say what the papers report.
primary ciliary dyskinesia (11 papers, 2018 to 2024). A rare, genetically heterogeneous, primarily respiratory disorder characterized by chronic upper and lower respiratory tract disease. "DNAH9 expressed on sperm tail is an important heavy chain component of the dynein arm of cilia and flagella, and mutation of DNAH9 leads to primary ciliary dyskinesia (PCD) and nonsyndromic asthenozoospermia." (PMID 36922987, 2023). "We report the first Japanese case of primary ciliary dyskinesia caused by DNAH9 variations." (PMID 33452233, 2021). "Previous research has noted the association of several other dynein heavy chain-encoding genes, such as DNAH1, DNAH5, DNAH9, and DNAH11, with ciliary primary dyskinesia (PCD) and laterality defects." (PMID 36459505, 2022). "Recent studies have demonstrated that mutations in other cilia dynein heavy-chain genes (such as DNAH5, DNAH9, and DNAH11) can cause primary ciliary dyskinesia (PCD)." (PMID 29843777, 2018). "It was reported that variants of DNAH9 (OMIM: 603330) might cause primary ciliary dyskinesia (PCD)." (PMID 33610189, 2021). "Discovery of new disease genes—Four genes, i.e., TTC12, GAS2L2, DNAH9 and DNAJB13, whose mutations are responsible for Primary Ciliary Dyskinesia (PCD) have been identified through molecular and cellular studies performed in the framework of the RaDiCo-DCP cohort." (PMID 34715889, 2021). "More importantly, DNAH9, DNAH11, PIH1D3, and SPAG1 were classified as primary ciliary dyskinesia (PCD) disease genes typically with AR inheritance; PIH1D3 follows X-linked recessive (XLR) inheritance." (PMID 35877578, 2022).
asthenospermia (4 papers, 2021 to 2023). "In summary, variants of DNAH9 are novel pathogenic factors for not only syndromic severe asthenospermia, such as PCD, but also nonsyndromic severe asthenospermia." (PMID 33610189, 2021). "It is also the first time to report that ICSI can be recommended for severe asthenozoospermia caused by DNAH9 variants." (PMID 33610189, 2021). "We identified DNAH9 as a novel pathogenic gene for nonsyndromic severe asthenospermia, and ICSI can contribute to favorable pregnancy outcomes for these patients." (PMID 33610189, 2021). "However, variants in DNAH9 lead to nonsyndromic severe asthenozoospermia have yet to be reported." (PMID 33610189, 2021). "Although mutations in DNAH9 have been identified to be an important cause of syndromic asthenospermia, such as PCD, the association between DNAH9 and nonsyndromic asthenospermia has not been examined." (PMID 33610189, 2021). "Of interest, variants in DNAH1 and DNAH9 genes, reported to be associated with PCD, have been depicted in patients with only male infertility, resulted from asthenozoospermia, without other ciliary disorders." (PMID 35692830, 2022).
breast carcinoma (3 papers, 2013 to 2022). "In our present study of a special type of breast cancer, we identified recurrent mutations of the DNAH9 gene (8% of the cases) by whole-exome sequencing analysis, a rate higher than that reported for luminal IDCs in the TCGA analyses (3%)." (PMID 24887297, 2014). "In breast cancer development there is little information on cilia involvement available, however, the cilia-associated genes Gli1 (Hh effector), RPGRIP1 (LCA) and DNAH9 (PCD) are commonly mutated in breast cancer." (PMID 23628112, 2013).
ciliopathy (3 papers, 2017 to 2022). A genetic disorder of the cellular cilia or the cilia anchoring structures, the basal bodies, or of ciliary function. "Loss-of-function mutations in DNAH9, which is a paralog of DNAH11, cause a motile ciliopathy characterized by LRA defects and mild respiratory beating defects in the distal ciliary region." (PMID 33139725, 2020). "Collectively, our results demonstrated that Dnah9 KD mice and an organoid model can recapture the clinical features of patients with PCD and provide an excellent drug screening platform for human ciliopathies." (PMID 35729109, 2022).
male infertility (3 papers, 2021 to 2024). The inability of the male to effect fertilization of an ovum after a specified period of unprotected intercourse. "As cilia or flagella are highly conserved in varieties of human cells and organs, the mutations of DNAH9 may be associated with multisystemic disorders, including bronchiectasis, recurrent respiratory tract infections, and male infertility, etc.." (PMID 33610189, 2021). "Four recessive (TRIOBP, SLC26A4, GJB2, COL4A3) and one dominant (SOX10) for the deafness; six recessive genes (LRGUK, DNAH9, ARMC4, DNAH2, RSPH6A, and ACE) for male infertility can be conclusively ascribed." (PMID 38884051, 2024).
hepatocellular carcinoma (2 papers, 2021 to 2024). A malignant tumor that arises from hepatocytes. "However, it has been recognized as among the ten most frequently mutated genes in cases of hepatocellular carcinoma and the loss of the wild type allele of DNAH9 identifying a suppressor in esophageal squamous cell carcinoma." (PMID 38277230, 2024).
Huntington disease (2 papers, 2022). Huntington disease (HD) is a rare neurodegenerative disorder of the central nervous system characterized by unwanted choreatic movements, behavioral and psychiatric disturbances and dementia. "The hub genes in gene set B were DNAI2, DNAI1, DNAH1, DNAH9 and DNALI1, all of which were enriched in Huntington’s disease." (PMID 36577966, 2022).
Respiratory tract infection (2 papers, 2021 to 2022). An infection of the upper or lower respiratory tract. "In the current study, we identified compound mutation of DNAH9 in a patient with PCD with the following clinical features: recurrent respiratory tract infections, low lung function, and ultrastructural defects of the outer dynein arms (ODAs)." (PMID 35729109, 2022).
asthma (1 paper, 2025). "Additionally, DNAH9 polymorphisms have been linked to asthma and bronchial hyperresponsiveness, particularly in response to early-life exposure to tobacco smoke." (PMID 40065384, 2025). "However, some DNAH9 mutations have been associated with chronic wet cough, asthma, bronchial hyperresponsiveness, and even jejunal atresia in rare cases." (PMID 40065384, 2025).
bone marrow failure (1 paper, 2020). "This includes genes mutated in rare hematological syndromes (ADA, GP6, IL17RA, PRF1, and SEC23B), reported in prior MDS/AML or inherited bone marrow failure (IBMF) series (DNAH9, SH2B3, and NAPRT1), or novel loci where loss-of- function of the identified germline variants was demonstrated (DHX34)." (PMID 32098966, 2020).
cataract (1 paper, 2025). Partial or complete opacity of the crystalline lens of one or both eyes that decreases visual acuity and eventually results in blindness. "Mutations in the DYNC1H1 gene, encoding a protein with functions and a structure very similar to those of DNAH9, cause cataracts." (PMID 40649110, 2025).
congenital heart disease (1 paper, 2025). A heart disease that is present at birth. "Typically, patients with DNAH9 mutations present with mild respiratory symptoms, sinusitis, and occasional ciliarelated complex congenital heart disease." (PMID 40065384, 2025).
diabetes (1 paper, 2025). "DNAH9 and TRP1 have not been previously associated with any diabetes or sex-hormone related traits." (PMID 40892850, 2025).
Hydrocephalus (1 paper, 2020). Hydrocephalus is an active distension of the ventricular system of the brain resulting from inadequate passage of CSF from its point of production within the cerebral ventricles to its point of absorption into the systemic circulation. "Around one month after birth, four of the six Dnah9 KO mice examined showed hydrocephalus." (PMID 33347437, 2020).
Hypertension (1 paper, 2016). The presence of chronic increased pressure in the systemic arterial system. "DNAH9 gene cluster is reported to be related to young-onset hypertension." (PMID 27980649, 2016).
hypospadias (1 paper, 2025). Hypospadias is the displacement of the urethral meatus on the ventrum of the penis. "There were no observed phenotypes of hypospadias or reduced penile development, which was consistent with previous studies showing that male mice heterozygous or homozygous for the DNAH8, DNAH9, and DNAH17 pathogenic mutations did not have the hypospadias phenotype." (PMID 41463044, 2025).
lung carcinoma (1 paper, 2016). "A total of 28 records are available in ClinVar with different variants of DNAH9 found in melanoma and lung cancer (April 28, 2015)." (PMID 26822197, 2016).
myeloma (1 paper, 2024). "Additionally, 23% of the mutations in our study (p = 3.1 × 10−10; OR = 3.8) were found in genes that are recurrently mutated in human myeloma (defined as a mutation present in at least 2 patients) including the BCL6 interacting factor Dnah9 and the immunomodulating factor Irf2bp2." (PMID 39198400, 2024).
Neonatal respiratory distress (1 paper, 2022). Respiratory difficulty as newborn. "Conversely, individuals with biallelic MNS1, DNAH9, CFAP53 or RSPH1 mutations have a lower prevalence of neonatal respiratory distress and a later and milder onset of respiratory symptoms." (PMID 36583018, 2022).
sinusitis (1 paper, 2025). An acute or chronic inflammatory process affecting the mucous membranes of any sinus cavity. "While sinusitis is a common feature among patients with DNAH9 mutations, it is noteworthy that four patients in the current study had normal nNO levels despite the presence of ciliary function-disrupting DNAH9 mutations." (PMID 40065384, 2025).
Situs inversus totalis (1 paper, 2022). "Dynein axonemal heavy chain 17 (DNAH17) is a protein of the DNAH family of which four genes have already been associated with autosomal recessive PCD, situs inversus totalis or heterotaxy, namely DNAH1, DNAH5, DNAH9, and DNAH11." (PMID 35474353, 2022).
small cell lung carcinoma (1 paper, 2021). Small cell lung cancer (SCLC) is a highly aggressive malignant neoplasm, accounting for 10-15% of lung cancer cases, characterized byrapid growth, and early metastasis. "TMEM132D and DNAH9 are cancer-associated genes in small cell lung cancer, and FDZ10 has a role in cancer reactivation." (PMID 33047283, 2021).
cancer (7 papers, 2016 to 2022). A tumor composed of atypical neoplastic, often pleomorphic cells that invade other tissues. "SLIT3, ABI3BP, MYOCD, PGM5, TNXB and DNAH9 are strongly associated with cancer initiation and progression." (PMID 36451444, 2022). "These variants were found in genes associated with cancers (ANKRD35, DNAH9, MAGEC1, TOX3) or participating in cancer-related signaling pathways (THSD1, MORN2, PTCRA)." (PMID 26822197, 2016). "Understanding the DNAH9 and FAT1 mutations may contribute to cancer surveillance and treatment." (PMID 35938006, 2022). "CD4+CD45RO+ T cells in the lesional blood highly expressed genes relating to cancer progression and CTCL pathogenesis: RGS1, RDH10, HES1, DNAH9, ANK2, and SGK1 16–25." (PMID 34608214, 2021).
infection (1 paper, 2023). The state of being infected such as from the introduction of a foreign agent such as serum, vaccine, antigenic substance or organism. "Moreover, DNAH9+-infected cell mapping within ALI epithelial cells revealed that ciliated cells were more susceptible to infection compared with other cell types, like DNAH9+ mature ciliated cells that are preferentially eliminated during SARS-CoV-2 infection." (PMID 37569398, 2023).
DNAH9 also shares sentences with these, for which no sentence is quoted: tumor (3 papers); gastric cancer (2); Airway obstruction (1); aneuploidy (1); atrioventricular septal defect (1); bladder cancer (1); bronchiectasis (1); Cirrhosis (1); colon adenocarcinoma (1); colon cancer (1); colorectal cancer (1); COVID-19 (1); deafness (1); esophageal squamous cell carcinoma (1); gastric adenocarcinoma (1); glioma (1); head and neck squamous cell carcinoma (1); immune deficiencies (1); immune disease (1); jejunal atresia (1); liver cancer (1); melanoma (1); myeloid malignancies (1); non-small cell lung carcinoma (1); oligoasthenoteratozoospermia (1); Onset (1); ovarian carcinoma (1); pulmonary arterial hypertension (1); situs inversus (1); skin cancer (1).
A further 1 disease shares a sentence with DNAH9 in 1 paper.